IL1B (interleukin 1 beta)
Diseases named in the same sentence as IL1B in open-access papers (continued):
Sharing a sentence is not in itself a finding about the gene and the disease.
periodontitis (continued). "Enhanced RANKL production and NF-κB signaling pathway activation by pro-inflammatory mediators, including IL-6, TNF-α, IL-1β, prostaglandin E2 (PGE2) and C3 are common in inflammatory diseases, including periodontitis and osteoporosis." (PMID 36359775, 2022). "Correlations between Vanins and clinical parameters, PD and CAL; between Vanins and inflammation, IL1B; and between Vanins and MPO in periodontitis were investigated by Spearman's correlation analysis respectively." (PMID 36527111, 2022). "Regarding individual biomarkers, IL-1β, IL-6, and MMP-8 levels were significantly higher in periodontitis patients (p ≤ 0.001, p < 0.05, respectively)." (PMID 35368315, 2022). "The present study analyzed salivary levels of IL-1β, IL-6, MMP-8, and IL-10 in periodontally healthy subjects and stage III periodontitis individuals." (PMID 35368315, 2022). "This is characterized by production of numerous mediators like IL-1β, IL-6, IL-8, and TNF-α, which are also involved in the progression of periodontitis." (PMID 34185172, 2022). "A previous study found that IL‐1β elevates the mRNA expression of HDAC6 in periodontal ligament fibroblasts, implying its pivotal role in periodontitis pathology." (PMID 36444635, 2022). "It reported that CU stops bone destruction related to periodontitis by regulating the RANKL and IL-1β markers level." (PMID 35453272, 2022). "A research study investigated IL-1β, IL-6, MMP-8, and IL-10 levels in healthy as well as periodontitis patients and found that IL-1β and IL-6 concentrations were significantly higher in periodontitis patients." (PMID 36289921, 2022). "One study identified several biomarkers using bioinformatics analysis, such as CSF3, CXCL12, IL-1B, MS4A1, PECAM1, and TAGLN, and they all served as predictors of diagnosis and prognosis in chronic periodontitis." (PMID 36457739, 2022). "Interleukin-1β (IL-1β) and tumor necrosis factor-α (TNF-α) are important cytokines in periodontitis, and their concentrations in GCF are higher with periodontitis." (PMID 35186787, 2022). "This is the first bioinformatics report describing the upregulation of necroptosis (IL-1B), pyroptosis IL-1B, TREM1, and FPR2, and ferroptosis (SLC2A3) related genes mainly in human periodontium infiltrated neutrophils during periodontitis." (PMID 36686646, 2022). "The aim of this study was to investigate the anti-inflammatory effects of DJLE by evaluating the inhibition of IL-1β, IL-6, TNF-α, iNOS, and COX-2 expression in hPDLCs to examine the potential to develop a treatment agent for periodontitis." (PMID 35455384, 2022). "We also found a decrease in serum pro-inflammatory factors IL-1β and IFN-γ, indicating that periodontitis inflammation was effectively controlled." (PMID 35932002, 2022). "Regarding intestinal tissue analyses, higher levels of IL-1β, IL-4, IL-6, IL-17A, IL17F, IL-21, IL-31, IL-33 and sCD40L were found in patients with IBD and periodontitis." (PMID 34501547, 2021). "In the presented study, we showed that the level of IL-1β in PISF in patients with implants was significantly lower than in GCF in patients with mild, moderate, or severe periodontitis." (PMID 33726736, 2021). "Here, the serum‐based three different cytokines (IL‐1β, IL‐6, TNF‐α) showed up‐regulated expression in periodontitis, which were consistent with previous studies." (PMID 34272761, 2021). "As elevated levels of LPS from gram-negative bacterial and inflammatory caspases were often detected in patients with periodontitis and in murine periodontitis, this provided a prerequisite for the activation of GSDMD and IL-1β release." (PMID 33869229, 2021). "IL-1β, ICPT, and Pg levels were significantly different between the periodontitis and gingivitis groups and yielded similar AUC values." (PMID 34001101, 2021).
periodontitis (continued). "However, during periodontitis, the immune response is a double-edged sword because the cytokines and antimicrobial components produced during the immune response, such as IL-17, IL-6, IL-1β, TNF-α, ROS, and NETs, can induce bone resorption and soft tissue injury." (PMID 33777839, 2021). "A periodontitis rat model was generated by ligatures around the first maxillary molar and then treated with caspase-4 specific inhibitor (Z-LEVD-FMK) or IL-1β antibody for 14 days." (PMID 33869229, 2021). "The IL-1β level in PISF in patients with implants was significantly lower than in GCF in patients with mild, moderate, or severe periodontitis." (PMID 33726736, 2021). "AT1-L knockout mice submitted to ligature-induced periodontitis (AT1-L group) and had a significantly lower level of IL-1β in gingival tissue compared to wild type animals (WT-L) (p < 0.05)." (PMID 34884653, 2021). "In chronic periodontitis, the nuclear expression of TNF- α, IL-1b, and IL-8 is significantly up-regulated following NF-kB activation." (PMID 34299815, 2021). "Proinflammatory cytokines, such as IL-1β, IL-6, and TNF-α, have been used as biomarkers to identify periodontitis and peri-implantitis." (PMID 34931168, 2021). "Regarding intestinal tissue analyses, higher levels of IL-1β, IL-4, IL-6, IL-17A, IL17F, IL-21, IL-31, IL-33 and soluble CD40 ligand (sCD40L) were found in patients having IBD activity and periodontitis." (PMID 34501547, 2021). "For discriminating health vs periodontitis groups, the predictor variables resulting from the CART analysis included HGF, MMP-9, LBP and IL-1b." (PMID 33742017, 2021). "Exploration of available transcriptomic datasets revealed C4A, C4B, CXCL12, FCGR3A, IL1B, and MMP3 as the top candidate molecular linkage genes between periodontitis and AD." (PMID 33869630, 2021). "Neutrophils in periodontitis also have a higher cytokine reactivity as the expression of chemokines and the release of cytokines (IL-1β, IL-6, IL-8, and TNF-α) are higher in neutrophils isolated from late-onset periodontitis patients." (PMID 33777839, 2021). "Their research work showed that IL-1β levels vary in GCF depending on periodontal conditions, with the highest concentration in mild to moderate periodontitis." (PMID 33726736, 2021). "Pro-inflammatory cytokines such as IL-1β, TNF-α and IL-6 are produced by monocytes, and macrophages and play a critical role in the pathogenesis of periodontitis." (PMID 34481488, 2021). "The prevalence of severe periodontitis in the OSAS group is 48.2%, and the levels of IL-1β in GCF and hs-CRP in serum are significantly higher in the OSAS group." (PMID 34205812, 2021). "In particular, GMSCs were treated with a culture containing inflammatory cytokines such as TNF-α, IL-1β, IFN-γ, IFN-α, and IL-3, and an inflammatory animal model was created in one study, ligature-induced periodontitis in mice." (PMID 33628266, 2021). "Upon stimulation with IL-23 and IL-1β, the expression of IFN-γ and IL-17A by ILC3s was markedly enhanced in periodontitis patients compared to healthy controls." (PMID 34381457, 2021). "Six genes C4A, C4B, CXCL12, FCGR3A, IL1B, and MMP3 were identified as the most significant crosstalk genes linking chronic periodontitis and Alzheimer's disease." (PMID 33869630, 2021). "Patients with Periodontitis and Peri-implantitis present higher levels of inflammatory markers such as IL-6, TGF-1β, IL-1β, and IL-8 compared to healthy patients." (PMID 34412595, 2021). "Together with IL-1β, TNF-α has been extensively studied in relation to periodontitis as a pro-inflammatory and immunomodulatory cytokine." (PMID 34408814, 2021). "Increase of such proinflammatory cytokines as: IL-1α, IL-1β, TNF-α, IL-6, and IL-17 were shown in patients with acute or chronic periodontitis." (PMID 33467650, 2021). "The combination of IL-1β, ICTP, and Pg exhibited the best AUC value (0.94) to discriminate periodontitis subjects from healthy subjects." (PMID 34001101, 2021).
periodontitis (continued). "The combination of IL-1β, ICTP, and Pg exhibited the highest efficacy for discriminating periodontitis subjects from healthy subjects (AUC = 0.94) and gingivitis subjects (AUC = 0.77)." (PMID 34001101, 2021). "Along with increased IL-1β processing, the activation of inflammasomes, such as NLRP3 and AIM2, is frequently detected in chronic periodontitis and aggressive periodontitis." (PMID 34177950, 2021). "There were also detectable levels of other inflammatory mediators such as TGF-β1, IL-1β, IL-2, IL-4, IL-10, IL-12p70, and IL-17A in the GCF samples of periodontitis patients." (PMID 34502071, 2021). "Previous studies have reported IL1B and TNF as key regulators in the periodontitis pathogenesis (Yucel-Lindberg and Båge, 2013), therefore it was not surprising to find these molecules highly represented in our cell interaction analysis." (PMID 33393902, 2021). "Elevated levels of IL-1β and IL-18 were detected in the gingival crevicular fluid (GCF), saliva, and serum of patients with periodontitis." (PMID 33562334, 2021). "The concentration of IL-1β, IL-6, and TNF-α was significantly higher in periodontitis patients than in healthy volunteers (P < 0.05)." (PMID 34592963, 2021). "In patients with periodontitis, the present study observed increased levels of pro-inflammatory factors IFN-γ, IL-1β, IL-2, IL-7, IL-21, and TNF-α, in addition to decreased levels of anti-inflammatory factors IL-5 in GCF of T2DM patients." (PMID 33417619, 2021). "The combination of IL-1β, ICTP, and Pg can be used to discriminate periodontitis subjects from healthy subjects and gingivitis subjects, and the combination of IL-1β and MMP-8 can be used to discriminate gingivitis subjects from healthy subjects." (PMID 34001101, 2021). "Serum‐based IL‐6, TNF‐α and IL‐1β, three different cytokines expression were demonstrated in PBMC of periodontitis and healthy controls." (PMID 34272761, 2021). "We found that the combination of IL-1β, ICTP, and Pg can be used to discriminate stage III periodontitis subjects from healthy subjects and gingivitis subjects." (PMID 34001101, 2021). "The concentrations of IL-1β, IL-6, and TNF-α were higher in periodontitis patients than in healthy controls." (PMID 34592963, 2021). "Among these 48 crosstalk genes and the chronic periodontitis-related genes in DisGeNET, C4A, C4B, CXCL12, FCGR3A, IL1B, and MMP3 were shared and identified as the most pivotal candidate links between periodontitis and AD." (PMID 33869630, 2021). "Our goal was to assess the efficacy of P. atlantica gel in improving experimentally induced periodontitis in Wistar rats by Histopathological analysis and evaluation of RANKL and IL-1β levels ELISA." (PMID 33321702, 2020). "For immunological parameters, the result showed a significant increase in serum mean levels of Il-1β and TNF-α in chronic periodontitis patients (A and B groups) as compared to healthy control subjects." (PMID 33083489, 2020). "Local ozone therapy inhibits the expression of inflammatory factors such as pentraxin-3 (PTX-3), IL-1β, and high-sensitivity C-reactive protein (Hs-CRP) in periodontitis patients." (PMID 32398953, 2020). "Despite the higher post-therapy expression of IL-1β in moderate sites of highly progressive patients, the ROC analysis showed small discrimination accuracy in stage III periodontitis." (PMID 33218047, 2020). "The cluster of mediators susceptible to inhibition by I-BET151 and JQ1 in gingival fibroblasts and GECs includes IL-6, IL-1β, and CCL2, elevated levels of which are most commonly found in patients with periodontitis." (PMID 33256844, 2020). "Accordingly, in our study, we evaluated the change in serum levels of pro-inflammatory and anti-inflammatory cytokines among periodontitis patients, and we found that they had higher significant levels of IL6, IL1b, and TNF compared to healthy individuals." (PMID 32604936, 2020).
periodontitis (continued). "F. alocis, a member of the genus Filifactor, is not only present at the site of periodontitis but has also been shown to induce the production of inflammatory cytokines such as TNF-α, IL-1β and IL-6 in vitro." (PMID 33121117, 2020). "Eight of these genes, including CXCL1, IL1B, IL6ST, and CD44, were consistently differentially methylated in participants with periodontitis-related traits." (PMID 33256844, 2020). "The extract showed a protective effect in the healing of periodontitis that had been induced in rats and decreased bone resorption by down regulation of serum RANKL and IL-1β markers." (PMID 33321702, 2020). "The pro-inflammatory cytokines IL-1β and tumor necrosis factor alpha (TNF)-α were frontrunner targets in the quest for molecular biomarkers of periodontitis activity." (PMID 33343358, 2020). "Mature IL-1β is a product of the inflammasome signaling pathway, which requires a second messenger, such as ATP; therefore, IL-1β may play a crucial role in the chronic process of periodontitis and cannot be used as an inflammation marker when the stimulation time is short." (PMID 33092290, 2020). "Thereby an increase of pro-inflammatory cytokines such as interleukin (IL)-1β, -2, -6, -8, tumour-necrosis-factor (TNF), and interferon-gamma (IFN-γ) was seen in periodontitis, while a decrease of inflammation was detected after periodontal treatment." (PMID 33153049, 2020). "The 5 ng/ml IL-1β and the 100 ng/ml IFN-γ reflect the corresponding cytokine levels in the gingival crevicular fluid (GCF) of periodontitis patients." (PMID 32423044, 2020). "Combining clinical measures, pathogen levels, and cytokines like interleukin (IL)-1β, osteoprotegerin (OPG) and matrix metalloproteinases (MMP)-8 can provide up to 74% sensitivity for predicting periodontitis progression." (PMID 33343358, 2020). "The level of IL‐1β in the GCF, which was the key cytokine in the development of periodontal disease, also increased in the T2DM group, periodontitis group and diabetic periodontitis group." (PMID 32794619, 2020). "Significantly higher levels of serum of cytokines IL-6, TNF-α and IL-1β, IL10, IL35, and TGF-β1 were measured in patients with chronic periodontitis when compared to the healthy control group." (PMID 32604936, 2020). "NLRP3 and IL1B genotypes and IL2 Haplotype Frequency Distributions in patients with periodontitis and controls." (PMID 31978095, 2020). "Yang et al27 found that inflammatory factors involved in periodontitis development, such as TNF‐α and IL‐1β, increased the proliferation ability of PDLSCs in vitro, which is consistent with the findings in this study." (PMID 31930698, 2020). "Among various inflammatory mediators, TNF-α, IL-1β, IL-6, and IFN-γ are the most effective proinflammatory cytokines during periodontitis." (PMID 32724318, 2020). "The presence of proinflammatory cytokines, such as IL-1β, TNF-α, and CRP, together with the presence of β-amyloid were found in the brain tissues of mice where periodontitis was induced by the inoculation of P. gingivalis in the periodontal tissue." (PMID 32054121, 2020). "In this high activity scenario, the reduction in IL-1β in both moderate and deep sites and TNF-α in deep sites of both periodontitis groups suggests a role for these cytokines in the disease process." (PMID 33218047, 2020). "In another study, the salivary macrophage inflammatory protein-1α, MM8, IL-1β, IL-6, prostaglandin E2 and TNF-α levels were reported to correlate with gingivitis and periodontitis development." (PMID 32646009, 2020). "The study is aimed at evaluating the effect of curcumin gel on serum levels of micronutrients (zinc, copper, and magnesium) and proinflammatory cytokines (IL-1β and TNF-α) in chronic periodontitis patients." (PMID 33083489, 2020). "A cohort study that included seven biomarkers showed that IL-1β, IL-6 and MMP-8 combination was the most sensitive and specific for discriminating health from periodontitis." (PMID 33081038, 2020).
periodontitis (continued). "Immunohistochemical staining of TNF-α, IL-1β and MMP-9 in mandible sections yielded a much stronger staining intensity in gingiva and PDL area from periodontitis induced rats compared to control rats, but this was mitigated in PDT treated rats." (PMID 31160615, 2019). "The present study analyzes the clinical periodontal parameters and the IL-1β and IL-37 levels in the GCF in generalized aggressive periodontitis patients before and after treatment with SRP and with or without additional diode or Er,Cr:YSGG laser therapy." (PMID 31308830, 2019). "Periodontitis-challenged group expressed a significant increase in the mRNA levels of TNF-α (P<0.001), IL-1β (P<0.0000001), COX-2 (P<0.000004), iNOS (p< 0.007), RANK (P<0.036), and RANK-L (P<0.05), when compared to naive group." (PMID 31682614, 2019). "The concentration of IL-1β and IFN-γ used in our experiments were similar to those observed in the gingival crevicular fluid (GCF) of periodontitis patients." (PMID 31847340, 2019). "BET inhibition significantly suppressed cytokine-induced mRNA expression of a broad range of inflammatory mediators involved in the pathogenesis of periodontitis, including IL8, IL1B, CCL2, CCL5, MMP3, and COX2." (PMID 31114581, 2019). "The TNF blockers used for the treatment of patients with RA resulted in significant reduction of biochemical markers of PD including IL-1β and IL-8 in the GCF of patients with established periodontitis." (PMID 31540277, 2019). "In a previous study, using P. gingivalis lipopolysaccharide, the upregulation of mRNA for IL-1β and FAS ligand was identified in a mouse periodontitis model." (PMID 31011284, 2019). "In periodontitis, TNF-α and IL-1β are actively present and are secreted by monocytes and macrophages, resulting in effects on the bone remodeling pathway." (PMID 31316593, 2019). "The maintenance of the inflammatory process is mediated by cytokines (TNF-α, IL-1β, IL-6, IL-8, IL-12, IL-17, IL-18, IL-23 and IFN-γ) in RA and in periodontitis." (PMID 30281626, 2018). "A study testing accuracy of the cumulative risk score calculated (CRS) from three salivary biomarkers (i.e., P. gingivalis, IL-1β, and MMP-8) was more accurate in the diagnosis of advanced periodontitis than any of the markers alone." (PMID 30305812, 2018). "This study evaluated the expression of pro-inflammatory (IL-1β, IL-6, IFN-γ and TNF-α) and anti-inflammatory (IL-4 and TGF-β) cytokines in apical periodontitis lesions." (PMID 29898177, 2018). "Serum levels of proinflammatory cytokines such as IL-1β, IL-6, and TNF-α were increased in a rat ligature-induced periodontitis model." (PMID 29576800, 2018). "We also showed overexpression of IL1B, TNFα, ICAM1, and RANKL mRNA in the palatal gingival tissues of periodontitis model rats, which is consistent with previous reports." (PMID 29091721, 2017). "Based on these results, we conclude that transfection of the NF-κB decoy ODN can suppress the overexpression of the downstream factors IL-1β, TNF-α, and ICAM-1 in the palatal gingival tissues of rats with periodontitis." (PMID 29091721, 2017). "In two recent studies conducted with women immediately after delivery, GCF levels of IL-1β, IL-6, TNF-α, and PGE2 and serum levels of TNF-α and PGE2 were significantly increased in women with periodontitis compared with periodontally healthy women." (PMID 29017560, 2017). "Previous research indicated that the expression of ICAM1 is regulated by certain inflammatory cytokines, including IL-1β and TNF-α, and that ICAM-1 plays an important role in the initial stage of periodontitis." (PMID 29091721, 2017). "In the experimental periodontitis model, NLRP3 and IL-1β were also enhanced, similar to the results of human periodontitis specimen." (PMID 29184853, 2017). "A previous study has shown that the concentration of IL-1β in GCF is 145±167 pg/ml in healthy subjects and 6452±2289 pg/ml in patients with chronic periodontitis." (PMID 27415426, 2016).